LCE5A (late cornified envelope 5A)
Description:
Precursors of the cornified envelope of the stratum corneum.
Synonyms: LEP18; SPRL5A
Tractability: No criterion of Open Targets' tractability assessment is met for any kind of drug.
Gene: Protein-coding gene on chromosome 1 (152,510,803 to 152,512,177, forward strand). Ensembl gene ENSG00000186207.
Pathways (Reactome):
Developmental Biology: Formation of the cornified envelope
Gene Ontology:
Molecular function: identical protein binding; protein binding
Biological process: epidermis development
Genetic constraint (gnomAD): Loss-of-function variants: 1 observed, 0.72 expected, observed/expected ratio (o/e) 1.38, 90% interval 0.31 to 1.91. That is too few expected variants to judge how well the gene tolerates losing a copy. Missense variants: 137 observed, 150.53 expected, observed/expected ratio (o/e) 0.91, 90% interval 0.79 to 1.05. Synonymous variants: 49 observed, 55.18 expected, observed/expected ratio (o/e) 0.89, 90% interval 0.7 to 1.13.
Homologues: Orthologues: macaque LCE5A (98% identical), chimpanzee LCE5A (97% identical), mouse Lce1e (76% identical), mouse Lce1g (71% identical), rat Lce1g (69% identical), pig LCE5A (65% identical). Paralogues in human: LCE2D (69% identical), LCE2A (69% identical), LCE2C (69% identical), LCE1E (68% identical), LCE1F (68% identical), LCE2B (68% identical), LCE1D (64% identical), LCE3D (49% identical), LCE3E (49% identical), LCE3B (48% identical), LCE3C (48% identical), LCE3A (47% identical), and 8 more.
Diseases named in the same sentence as LCE5A in open-access papers:
LCE5A is named in the same sentence as 2 diseases in open-access papers, as found by Europe PMC text mining. Sharing a sentence is not in itself a finding about the gene and the disease. The quoted sentences say what the papers report.
head and neck squamous cell carcinoma (1 paper, 2023). A squamous cell carcinoma that arises from any of the following anatomic sites: lip and oral cavity, nasal cavity, paranasal sinuses, pharynx, larynx, and salivary glands. "In head and neck squamous cell carcinomas (HNSCCs), the expression of the long non-coding RNA (lncRNA) lnc-LCE5A-1 and lnc-KCTD6-3 was associated with reduced overall survival, while the ectopic expression of this lncRNA decreased Vimentin mRNA levels and impaired HNSCC cell migration in vitro." (PMID 38067168, 2023).
psoriasis (1 paper, 2024). An autoimmune condition characterized by red, well-delineated plaques with silvery scales that are usually on the extensor surfaces and scalp. "Other psoriasis-specific enriched pathways included lipid metabolism (e.g. ACOT4, S1PR3), keratinization (e.g. LCE5A, KRT5/7/16), neutrophil degranulation, and antimicrobial peptides (e.g. LTF, DEFB4A, S100A7-9)." (PMID 38433843, 2024).